TNFAIP3 (TNF alpha induced protein 3)
Diseases named in the same sentence as TNFAIP3 in open-access papers (continued):
Sharing a sentence is not in itself a finding about the gene and the disease.
systemic lupus erythematosus (64 papers, 2009 to 2025). An autoimmune multi-organ disease typically associated with vasculopathy and autoantibody production. "In another example, a systemic lupus erythematosus-associated variant (termed TT > A) situated within an enhancer downstream of TNFAIP3 has been shown to abrogate NF-kB binding, affecting TNFAIP3 expression." (PMID 34414474, 2021). "Mutations in A20/TNFAIP3 locus have been associated with inflammatory diseases/conditions such as rheumatoid arthritis, systemic lupus erythematosus, and coronary artery disease." (PMID 33317598, 2020). "The TNFAIP3 region on chromosome 6q23 has previously been associated with RA and systemic lupus erythematosus pointing to its general role in the regulation of the immune response." (PMID 23152861, 2012). "TNFAIP3, an RA candidate gene, flanks this region, and polymorphisms in both the TNFAIP3 gene and the intergenic region are associated with systemic lupus erythematosus." (PMID 19292917, 2009). "Perfect proxies of rs10499194OLIG3/TNFAIP3 are also associated with a risk of systemic lupus erythematosus." (PMID 19445664, 2009). "We describe four unrelated patients evaluated at a single tertiary center, each carrying a distinct TNFAIP3 mutation and exhibiting a unique clinical picture ranging from mucocutaneous ulcerations and Behçet-like vasculitis to lupus-like autoimmunity and periodic fever with arthritis." (PMID 40822695, 2025). "However, patients with TNFAIP3 mutations presented additional autoinflammatory disease phenotypes, including systemic lupus erythematosus, psoriatic arthritis, autoimmune hepatitis, nephrotic syndrome, and Hashimoto’s thyroiditis." (PMID 39125844, 2024). "A pair of single nucleotide polymorphisms (rs148314165, rs200820567) 42 kb downstream from the promoter of TNFAIP3, have been proposed as the variants responsible for association with systemic lupus erythematosus based on comprehensive genetic and bioinformatic analyses." (PMID 24039598, 2013). "This study aimed to functionally characterize an enhancer ∼55 kb upstream of the TNFAIP3 promoter marked by the systemic lupus erythematosus (SLE) risk haplotype index SNP, rs10499197." (PMID 36199584, 2022). "Among the 637 peak-gene linkages unique to lupus, 78 ATAC-Seq peaks were linked to 29 genes in the TNF-α signaling pathway, including TNFAIP3." (PMID 39688922, 2024). "The genetic analysis detected at least one variant in 11 (26.1%) children, 5 (45.4%) with cSLE (ADAR, TNFAIP3, RNASEH2B, SHOC2, IFIH1) and 6 (54.5%) with lupus-like phenotype (TREX, DNASE1,RNASEH2B, C1S, TLR7, STAT5A, TNFRSF13B)." (PMID 36096831, 2022). "Other studies on systemic lupus erythematosus (SLE) and type 2 diabetes reported that some of the single nucleotide polymorphisms (SNPs) could influence the expression level of the TNFAIP3." (PMID 32398022, 2020). "TNFAIP3 is a ubiquitin-editing enzyme that negatively regulates multiple NF-κB signaling pathways and dysregulation of TNFAIP3 is related to systemic lupus erythematosus (SLE)." (PMID 26110642, 2015). "At least three of the lupus-associated genes are involved in TLR signaling, including IRF5, IRAK1, and TNFAIP3." (PMID 20886024, 2010). "In addition, the rs6920220 SNP – together with SNPs in the TNFAIP3 gene – have been found to be reproducibly associated with systemic lupus erythematosus (SLE) susceptibility." (PMID 19292917, 2009). "Also, SLE susceptibility SNPs of TNFAIP3 interact with those of UBE2L3, and these variations act synergistically to activate NF-κB, thereby increasing the risk of lupus." (PMID 38329126, 2024). "Furthermore, TNFAIP3 rs2230926 polymorphism has been demonstrated to be significantly associated with systemic lupus erythematosus (SLE) among multiple ethnic populations and other autoimmune diseases such as Sjögren’s syndrome, Crohn’s disease, psoriasis and rheumatoid arthritis." (PMID 25890346, 2015).
systemic lupus erythematosus (continued). "In mice, the overexpression of TNFAIP3 inhibits NLRP3 inflammasome complex, preventing lupus inflammation and renal injury." (PMID 37252693, 2023). "In a recent study of systemic lupus erythematosus (SLE), the circGARS/miR-19a signaling pathway was shown to regulate the expression of YTHDF2 to alter the activation of the immune response, which was mediated by tumor necrosis factor alpha-induced protein 3 (TNFAIP3)." (PMID 36810108, 2023).
lymphoma (41 papers, 2012 to 2025). A malignant (clonal) proliferation of B- lymphocytes or T- lymphocytes which involves the lymph nodes, bone marrow and/or extranodal sites. "In the established lymphomas, NF-κB activity is further enforced by mutations in various genes regulating NF-κB activity (e.g., TNFAIP3, MYD88), as well as recurrent chromosomal translocations affecting NF-κB pathway components in a subset of cases." (PMID 35267569, 2022). "In ocular adnexal MALT lymphoma, complete TNFAIP3 inactivation is associated with reduced lymphoma-free survival." (PMID 35008340, 2021). "A coding TNFAIP3 variant (rs2230926) has been correlated to lymphoma development in patients with SS of French and UK origin." (PMID 33255258, 2020). "Previously, A20/TNFAIP3 loss-of-function mutations were only identified as somatic variants in lymphomas [reviewed in Ref." (PMID 29515565, 2018). "Of interest, the TNFAIP3 rs2230926 variant occurred in one-fifth of the patients with younger-onset SS (≤40 years) complicated by lymphoma." (PMID 30662920, 2018). "We postulate that deregulation of the NF-κB pathway as a result of the TNFAIP3 rs2230926 aberration increases SS and SS lymphoma susceptibility particularly in patients with early disease onset." (PMID 30662920, 2018). "In the current study, the TNFAIP3 rs2230926 mutant variant emerged as a risk factor for both primary SS and SS-related lymphoma susceptibility." (PMID 30662920, 2018). "The association of TNFAIP3 polymorphisms with lymphoma in patients with Sjögren’s also highlights the potential role of A20 in regulating B cell hyperactivity and malignant transformation leading to lymphomagenesis." (PMID 28456914, 2017). "Most recently, genetic variations in complement C3 and germinal and somatic abnormalities of the A20 (TNFAIP3) gene, as well as vitamin-D deficiencies, have been associated with lymphoma in patients with pSS." (PMID 23853604, 2013). "Our study found that TNFAIP3 was one of the most frequently mutated gene in tMZL samples (tMZL22, tMZL35), which has been previously reported to be frequently mutated in lymphomas." (PMID 39460552, 2024). "TNFAIP3 deletions have been associated with Epstein–Barr viral infection in lymphomas." (PMID 37892185, 2023). "Interestingly, TNFAIP3 mutations rarely co-existed with mutations with other genes, supporting their important pathogenetic role in these lymphomas." (PMID 35008340, 2021). "In SS, a germline and coding polymorphism of TNFAIP3 (A20), a central gatekeeper of NF-kB activation, was found associated with lymphoma, linking the impaired control of NF-kB activation in B cells to autoimmunity and to the risk of lymphoma." (PMID 34322134, 2021). "Biallelic somatic loss-of-function mutations of TNFAIP3 drive the onset of malignant lymphoma due to the excess activation of NF-κB signaling, and the associated problem of interpreting the effects of missense mutations of TNFAIP3 is similar to that on the onset of HA20." (PMID 33549127, 2021). "Additionally, somatic mutations and polymorphisms in the TNFAIP3 gene have been also reported in several types of lymphomas including lymphomas of mucosal marginal zone (MALT), which is the major type of SS-related lymphoproliferative disease." (PMID 26550578, 2015). "In a comprehensive French study with 87 HCV-associated lymphoma patients, the TNF alpha induced protein 3 (TNFAIP3)/A20 gene’s rs2230926G allele was found more frequently in patients exhibiting rheumatoid factor (RF) activity (20%)." (PMID 38654358, 2024). "In this regard, it is of interest that also in this disorder the clonally expanded rogue B-cells harbor mutations of lymphoma-related genes (CARD11, TNFAIP3, CCND3, ID3, BTG2, KLHL6)." (PMID 39055707, 2024). "The role of TNFAIP3 (TNF-alpha-induced Protein 3, modulating NF-kB activation) has also been suggested in both pSS-related lymphomas and mycobacterial susceptibility." (PMID 36173925, 2022).
lymphoma (continued). "In various forms of lymphoma, TNFAIP3 plays a tumor suppressive role, due to inactivated gene mutations, deletions, and promoter methylation." (PMID 36033828, 2022). "TNFAIP3, also known as A20, represents a tumor suppressor gene in lymphomas that synergistically attenuates NF-κB signaling induced by tumor necrosis factor (TNF) and TLR signal transduction." (PMID 35937947, 2022). "In light of these results, we further focused on deregulated miRNAs and their putative interactions with B-cell specific transcription factors SPI1 and ELF-1 attenuated in cHL and also the NF-ĸB inhibitor TNFAIP3 recurrently inactivated in this lymphoma." (PMID 34201504, 2021). "Both SS-lymphoma and SS-non lymphoma subsets exhibited higher frequencies of TNFAIP3 coding variation compared to HC (8.8% (8/91) vs. 7.6% (18/236) vs. 3.6% (16/448), respectively)." (PMID 30662920, 2018). "As an important player in the NF-κB pathway by various mechanisms, TNFAIP3 acts as a tumor suppressor gene in various lymphoma subtypes." (PMID 25922601, 2015). "In cases of MALT and other lymphomas, TNFAIP3 has been postulated to work as a tumor-suppressor gene." (PMID 23039325, 2012). "TNFAIP3, which encodes the A20 deubiquitinase that activates noncanonical NF-κB signaling, is frequently lost in lymphoma where it promotes lymphomagenesis." (PMID 40111422, 2025). "Additionally, inactivating somatic mutations or deletions have been reported in the tumor suppressor gene, ubiquitin-editing protein A20 (or TNFAIP3) across many types of lymphomas including MALT and FL." (PMID 36672402, 2023). "For example, A20 reexpression in lymphoma-derived cell lines lacking functional TNFAIP3 alleles induces cell cycle arrest/cell death with concomitant down-regulation of constitutive NF-κB activation." (PMID 34269817, 2021). "In pSS, a germline missense polymorphism in TNFAIP3, a gene coding for an important negative feedback regulator of the NF-κB pathway, is associated with lymphoma development, particularly in patients with early disease onset." (PMID 32201227, 2020). "Indeed, till now, very few studies have investigated the genetic involvement in lymphoma in SS, and only few associations have been identified, e.g., with the MHTFR, BAFF, and TNFAIP3 genes." (PMID 30882006, 2019). "Furthermore, they fit with the hypothesis of a “two-hit” process, in which a combination of germline and somatic abnormalities of TNFAIP3 promote the development of lymphoma." (PMID 29707540, 2018). "Moreover, the rs2230926 exonic variant of the Tumor Necrosis Factor, Alpha-Induced Protein 3 (TNFAIP3) gene, encoding a defective A20 protein, along with the BAFF-R His159Tyr mutation, have been detected in increased frequency among young SS patients (≤40 years) complicated with lymphoma." (PMID 33567548, 2021). "We also found CNA from our assay could also reveal some lymphoma critical genes, such as TNFRSF14 in 1p36.32, TNFAIP3 in 6q23.3, and SETD2 in 3p21.31." (PMID 38313801, 2024). "On the other hand, sOPN induces NF-κB signaling by acting on cell surface receptors via an autocrine loop without significant change in A20/TNFAIP3 and ABIN1/TNIP1 in lymphoma cells." (PMID 27050077, 2016).
Autoimmunity (28 papers, 2011 to 2025). The occurrence of an immune reaction against the organism's own cells or tissues. "TNFAIP3 has previously been implicated in the resolution of chronic inflammation and prevention of autoimmunity." (PMID 40723157, 2025). "This locus coincides with the TNFAIP3 gene region, an immune regulator known to be associated with autoimmunity." (PMID 41425598, 2025). "LOF variants in genes that negatively regulate the activation of NF-κB, such as those encoding deubiquitinases OTULIN or TNFAIP3/A20, lead to uncontrolled inflammation, autoimmunity, and autoinflammatory diseases." (PMID 38593810, 2024). "TNIP1 encodes a TNF-α-induced protein 3 (TNFAIP3 or A20)-binding protein which plays a role in autoimmunity and tissue homeostasis through the regulation (repression) of NF-κB activation downstream of TNF-α and Toll-like receptors." (PMID 33581710, 2021). "Germline loss-of-function mutations in TNFAIP3 leading to A20 haploinsufficency have also been shown to cause Behcet-like autoimmunity, which is characterised by mucosal ulcers and eye inflammation." (PMID 34269817, 2021). "Conditional A20/Tnfaip3-floxed alleles enabled lineage-specific Tnfaip3-deletion and study of cell-specific contributions to autoinflammation and autoimmunity." (PMID 29515565, 2018). "The list of common coding and non-coding variants (SNPs) in the vicinity of the TNFAIP3 gene region associated with autoimmune conditions keeps expanding, with recently reported associations with autoimmune hepatitis (AIH), primary biliary cirrhosis and colitis ulcerosa." (PMID 29515565, 2018). "It is likely that multiple distinct variants of TNFAIP3 could differentially modulate risk of autoimmunity in different diseases and different ancestral backgrounds." (PMID 23555688, 2013). "In addition to RIPK1 variants, variants of proteins that can regulate RIPK1 ubiquitination and phosphorylation, such as variants in the TNFAIP3 gene, which encodes the protein A20, are linked with autoimmunity and inflammation, and likely also contribute to irregularities of RIPK1 function." (PMID 41019071, 2025). "In the study, TNFAIP3 was abnormally expressed in the cecum tissues of diarrheal rabbits, indicating that diarrhea might cause damage to cecum barrier function and adversely affect autoimmunity in rabbits." (PMID 35565618, 2022). "Multiple variants of TNFAIP3 could modulate development of autoimmunity in different diseases." (PMID 26339139, 2015). "ROQUIN destabilizes TNFAIP3 mRNA, leading to lower A20/TNFAIP3 protein expression, and mutated ROQUIN is known to induce autoimmunity in mice." (PMID 29515565, 2018). "The loci that were associated with the largest number of ADs include IL23R, TNFAIP3, and IL2RA, supporting an important role for T cell and innate immune response pathways in autoimmunity." (PMID 22174698, 2011). "That two distinct disease‐associated loci have similar functional consequences highlights the importance of TNFAIP3 in human autoimmunity and may point to cell type‐specific effects." (PMID 32239644, 2020). "In addition, aberrant TNFAIP3 signaling also leads to increased IL-6 production in dendritic cells, implicating TNFAIP3 in the development of autoimmunity in dendritic cells as well as B-cells." (PMID 33043033, 2020). "A recent study demonstrated that lack of TNFAIP3 in B cells resulted in overexpression of pro-inflammatory cytokines, which caused inflammation and autoimmunity in aged mice." (PMID 28702029, 2017).
breast carcinoma (24 papers, 2009 to 2026). "TNFAIP3 was strongly associated with the infiltration of all types of immune cells in breast cancer, and CXCL10 and IFNG behaved similarly in all immune cell types except macrophages." (PMID 33102239, 2020). "However, polymorphisms alter to predict the response to metastatic breast cancer chemotherapy and tumor necrosis factor, α-induced protein 3 (TNFAIP3) gene mutation in oral squamous cell carcinoma." (PMID 27275739, 2016). "There exists a strong correlation between TNFAIP3 mRNA and protein levels in breast cancer (ρ = 0.69, p < 0.001)." (PMID 41461391, 2026). "Our comprehensive multi‐omics analysis reveals TNFAIP3 as a critical regulator of breast cancer progression and tumor immunity." (PMID 41461391, 2026). "At the protein level, the induction of Cd274 and Tnfaip3 was confirmed in breast cancer stem cells under salinomycin treatment." (PMID 38201582, 2023). "Anti‐tumor effects of TNFAIP3 were shown in B cell lymphoma, colorectal carcinoma, and hepatocellular carcinoma, but TNFAIP3 acts as an oncogene in breast cancer, gastric cancer, and melanoma." (PMID 36056685, 2023). "Basal and TNBC subtypes of breast cancers overexpressed CD274 conjointly with three ferroptosis drivers: TNFAIP3, IFNG and IDO1 (IDO1: inhibitory immune checkpoint)." (PMID 38201582, 2023). "Other metastases genes associated with poor prognosis in breast cancer, such as CEACAM6, COL17A1, CXCL8, TNFAIP3, SEMA7A and L1CAM, are also attenuated with SP receptor antagonist treatment." (PMID 34359773, 2021). "While, TNFAIP3 was also thought to be an oncogene in numbers of solid tumors such as ductal carcinoma in situ, gastric carcinoma, basal-like breast cancer." (PMID 34526012, 2021). "Overexpression of CXCL10 is considered to be a favorable prognostic factor in TNBC, and high levels of TNFAIP3 expression are correlated with poor overall survival in HER2+ breast cancer and TNBC." (PMID 33102239, 2020). "In summary, our results indicate that TNFAIP3 is essential for FGFR1 signaling-induced breast cancer cell growth in culture and tumor growth in vivo." (PMID 30111373, 2018). "Interestingly, ALDH-positive breast cancer stem cells (BCSCs) were reduced in TNFAIP3 knockout in BCSCs, possibly since TNFAIP3 facilitated the growth of ALDH-positive BCSCs in part through the FGFR1/MEK/ERK pathway." (PMID 40469292, 2025). "Additionally, TNFAIP3 promoted epithelial-mesenchymal transition (EMT) in TGF-β1-induced breast cancer cells by facilitating multiple monoubiquitinations of Snail." (PMID 40469292, 2025). "Tnfaip3 transcription is also increased in doxorubicin-treated breast cancer cell lines." (PMID 39285385, 2024). "In addition, overexpression of several miRNAs, such as miR-125b and miR-668, leads to NF-κB activation by targeting TNF alpha induced protein 3 (TNFAIP3/A20) and IκBα, respectively, thus promoting radioresistance in nasopharyngeal carcinoma and in breast cancer." (PMID 35814425, 2022). "Among the genes consecutively upregulated by AP20187-activated iFGFR1, we were particularly interested in understanding how FGFR1 signaling regulates TNFAIP3 expression, since it plays an important role in NF-κB regulation but its role in breast cancer is unknown." (PMID 30111373, 2018). "However, other studies have reported the cancer-promoting roles for TNFAIP3 in conferring tamoxifen resistance in ER+ breast cancers, promoting EMT and metastasis of basal-like breast cancers by mono-ubiquitination of SNAIL1, and preventing adult T-cell leukemia cells from apoptosis." (PMID 30111373, 2018). "In breast cancer, for instance, OTUB1, YOD1, OTUD5, OTULIN, TNFAIP3, and ZRANB1 drove chemoresistance, whereas OTUD1 and OTUD3 were sensitized to chemotherapy." (PMID 40469292, 2025). "The dual roles of OTU family members in specific cancers present intriguing mechanistic complexities, exemplified by OTUB1 in breast cancer, OTUD7B in lung cancer, and TNFAIP3 in CRC." (PMID 40469292, 2025).